TMEM114 (transmembrane protein 114)
Tractability: Antibody: UniProt places it where antibodies can reach, with medium confidence; UniProt predicts a signal peptide or a membrane-spanning region; its Gene Ontology location is reachable by antibodies, with medium confidence.
Gene: Protein-coding gene on chromosome 16 (8,537,605 to 8,590,511, reverse strand). Ensembl gene ENSG00000232258.
Subcellular location: Cell junction, tight junction; Lateral cell membrane; Apical cell membrane
Gene Ontology:
Molecular function: protein binding
Cellular component: apical plasma membrane; lateral plasma membrane; apicolateral plasma membrane; bicellular tight junction; membrane
Genetic constraint (gnomAD): Loss-of-function variants: 9 observed, 9.41 expected, observed/expected ratio (o/e) 0.96, 90% interval 0.57 to 1.63. That is too few expected variants to judge how well the gene tolerates losing a copy. Missense variants: 218 observed, 164.15 expected, observed/expected ratio (o/e) 1.33, 90% interval 1.19 to 1.49. Synonymous variants: 104 observed, 76.98 expected, observed/expected ratio (o/e) 1.35, 90% interval 1.15 to 1.59.
Homologues: Orthologues: chimpanzee TMEM114 (99% identical), macaque TMEM114 (97% identical), pig TMEM114 (91% identical), guinea pig TMEM114 (89% identical), dog TMEM114 (88% identical), mouse Tmem114 (85% identical), rat Tmem114 (83% identical), tropical clawed frog tmem114 (54% identical), zebrafish TMEM114 (51% identical). Paralogues in human: TMEM235 (41% identical).
Diseases named in the same sentence as TMEM114 in open-access papers:
TMEM114 is named in the same sentence as 1 disease in open-access papers, as found by Europe PMC text mining. Sharing a sentence is not in itself a finding about the gene and the disease. The quoted sentences say what the papers report.
cataract (1 paper, 2025). Partial or complete opacity of the crystalline lens of one or both eyes that decreases visual acuity and eventually results in blindness. "Knockout of mammalian homologs of cataract-associated genes, such as TMEM114, CHRLD1, SIPAL3, or CELF1, results in ocular phenotypes loosely associated with cataracts." (PMID 41210874, 2025).